IGF1 (insulin like growth factor 1)
Diseases named in the same sentence as IGF1 in open-access papers (continued):
Sharing a sentence is not in itself a finding about the gene and the disease.
diabetes (continued). "A recent study examined prospective associations of serum IGF1 with mortality, dementia, vascular disease, diabetes, osteoporosis and cancer—finding two generalized patterns." (PMID 34769292, 2021). "Endocrine disorders such as diabetes, thyroid function disorder, low levels of Vitamin D, sex, steroid abnormalities, reduced growth hormone/IGF-1, and malnutrition have also been associated with osteosarcopenia." (PMID 32764814, 2020). "IGF1 can influence Aβ clearance from the brain by promoting Aβ transport over the blood-brain barrier, unbalanced β-amyloid, occurring in diabetes is associated with neurite degeneration and neuronal loss, highlighting the correlation between AD and diabetes." (PMID 33585009, 2020). "Low IGF1 secretion is known to cause growth restriction in childhood, as well as deregulated lipid metabolism, cardiovascular disease, and diabetes in adulthood." (PMID 32678007, 2020). "Significant inverse associations were observed between plasma IGF1 and eGFR, the prevalence of diabetes mellitus as primary renal disease, the cumulative prednisolone dose, AST, and GGT, and the time between transplantation and baseline measurements." (PMID 31973007, 2020). "Significant inverse associations were furthermore revealed between plasma IGF1 and age, eGFR, the prevalence of diabetes mellitus as primary renal disease, and GGT." (PMID 31973007, 2020). "In humans, diabetes mellitus is associated with the GH/IGF-1 axis, GFR, renal hypertrophy, and microalbuminuria." (PMID 31540583, 2019). "A previous study showed that total insulin and IGF1 resistance in pancreatic β cells causes overt diabetes." (PMID 30778335, 2019). "Genetic analyses of several bat species have shown differences in the growth hormone (GH)/insulin-like growth factor 1 (IGF1) axis which in humans is associated with aging, resistance to diabetes and cancer." (PMID 30294323, 2018). "In a prospective study involving serial maternal IGF-1 measurements in women with pre-existing diabetes, IGF-1 was significantly positively associated with macrosomia." (PMID 30108547, 2018). "Considering all the women with diabetes together, third trimester IGF-1 was positively associated with birthweight percentile, explaining 24% of the variation in birthweight." (PMID 30108547, 2018). "we mimicked polyglandular deficiency syndrome in both immature and prepubertal mice by induction of diabetes and hypothyroidism, which caused decreases in serum concentrations of testosterone and insulin like growth factor 1 (IGF-1)." (PMID 29940839, 2018). "Of the top 20 beta cell disallowed genes, increased expression of six was associated with diabetes with an adjusted p-value < 0.1, with IGF1 showing the most significant association." (PMID 28443133, 2017). "An aberrant IGF-1 axis is implicated in many diseases, such as rheumatic diseases, cardiovascular diseases, diabetes and cancer, as well as infertility." (PMID 28706275, 2017). "Type 2 diabetes mellitus has been linked with bone fragility via multiple proposed mechanisms, including reduced insulin growth factor-1 (IGF1) production, vitamin D deficiency and increased circulating advanced glycation end-products (AGE)." (PMID 28158241, 2017). "Of interest, a relationship between IGF‐1 and several cardiovascular risk markers has been found, some of them being arterial hypertension, diabetes, endothelial dysfunction, and carotid intima‐media thickness." (PMID 29152285, 2017). "Of the top 20 beta cell disallowed genes, IGF1 showed the strongest association with diabetes status (p = 0.0185), whereas the association with increased IGFBP4 was less strong (p = 0.0786)." (PMID 28443133, 2017). "This gene is the main regulator of IGF-1 bioactivity and it has been found to play a major role in the development of diabetes and associated complications." (PMID 28103909, 2017).
diabetes (continued). "A univariate Cox regression analysis showed that age, diabetes mellitus, history of cardiovascular disease, low IGF-1, high CRP, high glucose, low LDL-cholesterol, J-DOPPS risk score, ARO risk score and high FGF21 were predictive for the all-cause mortality." (PMID 28582462, 2017). "Multiple studies (in vitro and in vivo) demonstrate the association between IGF-1 deficit and deregulated lipid metabolism, cardiovascular disease, diabetes, and an altered metabolic profile of diabetic patients." (PMID 26733412, 2016). "For example, lowering insulin/IGF-1 signaling in worms and flies extends lifespan but can cause diabetes and cardiovascular disease in human." (PMID 26934328, 2016). "A challenging diagnostic issue presents in patients with diabetes mellitus, because these patients can have an abnormal IGF-1 level or an abnormal response to OGTT (or both)." (PMID 27716353, 2016). "Low levels of insulin or IGF-1 and elevated levels of glucocorticoids induce the loss of muscle protein in diabetes, and insulin resistance is a characteristic feature of many systemic diseases with muscle wasting." (PMID 26856534, 2016). "Recently, accumulating evidence has cast a spotlight on type 2 diabetes mellitus as a potent risk factor for AD development, which is likely to be mediated by insulin and insulin-like growth factors (IGF-1, IGF-2)." (PMID 26556341, 2015). "Diabetes produces defects in wound healing, which is linked to hyperglycemia-induced negative regulation of insulin-responsive growth factors, such as insulin-like growth factor-1 (IGF-1)." (PMID 26681965, 2015). "While hyperglycemia is a major factor, diabetes is associated with changes in insulin, IGF-1 and many other hormones and metabolites, including free fatty acid, amino acids, advanced glycation end products, and components of the oxidative stress pathway." (PMID 26075045, 2015). "Studies show that the association between IGF-1 levels and diabetes risk form a U-shaped curve, indicating that people with either low or high levels of IGF-1 possess a higher risk of developing type 2 diabetes." (PMID 25120532, 2014). "Diabetes mellitus, as a risk factor for endometrial cancer (EC), causes an increase in insulin and IGF-1 concentrations in the blood serum." (PMID 24308813, 2013). "Aside from the effects of GH and IGF-1 directly on peripheral tissues, morbidity and mortality of patients with this disease is strongly associated with diabetes mellitus, hypertension, and cardiovascular disease." (PMID 24039977, 2013). "Diabetes as a risk factor in EC increases insulin and IGF-1 blood levels, both considered mitogenic factors contributing to the development of many cancers via enhanced cell proliferation." (PMID 24308813, 2013). "Insulin, insulin-like growth factor-1, and neurotrophin intranasal delivery has been suggested as a way to compensate for the neural damage caused by diabetes, stroke, diabetes, Alzheimer's disease, and HIV." (PMID 23431469, 2013). "IGF-1 has been considered as a target candidate gene of genetic association studies for numerous human diseases, including diabetes, diabetic retinopathy (DR), cancer susceptibility, osteoarthritis, bodyweight, growth, menarche, and longevity." (PMID 22509095, 2012). "Genetic studies revealed that the ablation of insulin/IGF-1 signaling in the pancreas causes diabetes." (PMID 22384192, 2012). "It has to be noted that decreases in circulating IGF-1 levels can result from various causes frequently encountered in critically ill patients, such as malnutrition, chronic liver disease or diabetes." (PMID 21291516, 2011). "For example, people with a high level of circulating IGF1 are more susceptible to cancers, while a low level of circulating IGF1 is a risk factor for cardiovascular diseases, premature atherogenesis, and diabetes." (PMID 20199671, 2010).
diabetes (continued). "Retained concentration of IGF-1 reduces the risk of diabetes, sarcopenia and cognitive attenuation and in elderly also the risk of ischemic heart diseases." (PMID 17212815, 2007). "Both diabetes and sarcopenia are associated with abnormal hormone secretion, which may lead to reduced secretion of testosterone, estrogen, and insulin-like growth factor 1 (IGF-1) among others." (PMID 40456103, 2025). "This is consistent with prior evidence: a prospective study showed that IGF-1 above the median halved the risk of glucose intolerance or diabetes over ~4.5 years, and a 7,777-subject European cohort revealed a U-shaped association, where both low and high IGF-1 increased diabetes risk." (PMID 41393761, 2025). "Additionally, since insulin and IGF-1 signaling associated with diabetes has been reported to be involved in the molecular mechanism of osteosarcopenia, it is possible that similar signaling is also involved in osteodynapenia." (PMID 39894806, 2025). "Insulin-sensitizing therapies such as metformin may exert a threefold effect by lowering the risk of diabetes progression, reducing insulin-mediated ovarian androgen synthesis, and decreasing IGF-1 levels." (PMID 41384021, 2025). "In terms of signaling pathways, and in cases of diabetes, reduced insulin levels and reduced insulin receptor expression are associated with AD and the defective activation of the insulin/IGF-1/PI3K/Akt pathway of intracellular signals, which is a major effector for insulin’s action in the brain." (PMID 39769243, 2024). "Low levels of IGF-1 and IGFBPs have been linked to diabetes and CVD risk." (PMID 38255276, 2024). "Besides, cytokine including adiponectin and INSR presented interesting association with diabetes due to the crucial correlation with IGF1 in our study." (PMID 38375323, 2024). "However, diabetes is associated with an increased cancer risk, explained by insulin-like growth factor 1 (IGF-1), IGF-1R, and the signaling pathway." (PMID 38774165, 2024). "Insulin-Like Growth Factor 1 (IGF-1) is a hormone that is associated with diabetes." (PMID 39519397, 2024). "The association between the IGF-1 index and low bone mass still existed (95% CI 0.02 (0.001–0.5), p=0.0209) even after adjusting for age, gender, CD duration, BMI, hypertension, dyslipidemia, diabetes, ALT, Scr, FT3, F24 pm, PTH, and osteocalcin." (PMID 37441368, 2023). "Furthermore, age-related reductions in IGF-1 correspond to increases in risk of hypertension, diabetes, and other cardiovascular diseases including ischemic stroke." (PMID 37371326, 2023). "Patients with very high or very low levels of serum IGF-1 are both at increased risk of diabetes." (PMID 36798135, 2023). "IGF-1 expression and hyperinsulinemia (acting alone or in parallel) associated with the onset of diabetes mellitus have been described as new and evolving factors that may explain the higher incidence of pancreatic cancer in Western populations." (PMID 35954223, 2022). "Clinical studies suggest that low IGF-1 levels are associated with diabetes and obesity." (PMID 35401920, 2022). "Conversely, in another prospective study it was shown that mutations in the growth hormone receptor (GHR) gene lead to reduced IGF-1 levels, which are associated with severe short stature in the subjects concerned and significantly reduced diabetes and BC risks." (PMID 36085535, 2022). "Untypical IGF-1 activity is very likely to be associated with diabetes-related vascular disorders and may even lead to cardiac dysfunction, but it is still obscure." (PMID 35454166, 2022). "The downregulation of kynurenine in the DLC group might be associated with decreased IGF-1 level under the condition of diabetes mellitus." (PMID 36329881, 2022).
diabetes (continued). "IRS1 (insulin receptor substrate-1) is an important gene associated with diabetes because it is a substrate for insulin receptor tyrosine kinase and plays a crucial role in insulin signaling, insulin-like growth factor-1 signaling and regulates insulin secretion by β cells in the pancreas." (PMID 36292779, 2022). "Whether such dysregulation in the abundance of IGF1 is a cause or consequence of diabetes remains unclear." (PMID 35741102, 2022). "A crosstalk between insulin and Igf-1 is mediated by the phosphorylation of Irs1 residues; thus, insulin/IGF-1 signaling could underlie the poor healing of injured muscles that is associated with diabetes." (PMID 33803124, 2021). "In addition, we investigated the association between IGF-1 admission levels and diabetes status at hospital discharge as well as post-ACS myocardial infarct size and dysfunction as measured by myocardial perfusion scintigraphy (MPS) at 6 weeks post-ACS." (PMID 34851758, 2021). "Indeed, several studies, both in-vitro and in-vivo have shown the association between low levels of IGF1 and altered lipid metabolism, cardiovascular disease and diabetes." (PMID 33692752, 2021). "Low IGF-1 is associated to IR, glucose intolerance, and diabetes." (PMID 33562271, 2021). "Moreover, significant positive correlations were noted between the hazard associated with high IGF‐1 and age for dementia (p=0.02), diabetes (p=0.001), vascular disease (p=0.002), osteoporosis (p=0.02), and mortality (p=0.005)." (PMID 34363732, 2021). "Therefore, the distinction between the roles of insulin and IGF-1 as causes of diabetes and progression of insulin-resistant states is unclear." (PMID 34239560, 2021). "Affected individuals exhibit muscle weakness, immune suppression, impairment of the GH/IGF1 axis, higher risk of diabetes, cardiovascular disease (hypertension), osteoporosis, decreased fertility, depression, and weight gain (Chabre, 2014; Ferraù and Korbonits, 2015)." (PMID 33724179, 2021). "Also, IGF-1 deficit has been reported to be significantly associated with the risk of developing impaired glucose tolerance, IR, and type 2 diabetes mellitus (T2D)." (PMID 33905470, 2020). "Of note, high IGF-1 bioavailability may prevent or delay the inception of diabetes-associated complications in diabetes patients." (PMID 33905470, 2020). "Importantly, low IGF-1 concentrations are associated with late mortality in patients with myocardial infarction, cardiac failure, and diabetes." (PMID 33905470, 2020). "Furthermore, a previous study showed that IGF-1 causes insulin activity and peripheral glucose utilizations to increase, hepatic glucose production to decrease, and lipid profiles in diabetes patients to improve." (PMID 33905470, 2020). "In addition, associations between low IGF1 and deregulated lipid metabolism, cardiovascular disease, diabetes, and altered metabolic profile of diabetic patients in adulthood have been reported." (PMID 32678007, 2020). "Low concentrations of IGF-1 have been associated with neuropathy and other diabetes complications." (PMID 33905470, 2020). "In addition, diabetes can impair the mTOR pathway, causing a reduction in IL-15 activation, leading to a reduction in IGF-1 and wound closure." (PMID 33291435, 2020). "From the limited number of studies that have assessed this relationship, data suggest that elevated IGF-1 and/or GH levels at diagnosis may be associated with arthropathy, heart disease, malignant neoplasms, diabetes mellitus, hypertension, and sleep apnea." (PMID 31741320, 2020). "Nonetheless, low IGF1 in early life is known to be associated with later risk of NCDs, particularly diabetes, and could mediate the hypothesized “thrifty phenotype” by regulating nutrition, growth and metabolism." (PMID 31255658, 2019). "GH and IGF-1 excess exerts many actions on cardiovascular system and acromegaly is still associated with several risk factors that contribute to atherosclerosis as hypertension, diabetes and dyslipidemia." (PMID 31396153, 2019).
diabetes (continued). "Low IGF1 in early life is known to be associated with later risk of NCDs, particularly diabetes, and could mediate the hypothesized “thrifty phenotype”." (PMID 31255658, 2019). "In diabetes, increased oxidative stress at low heme oxygenase-1 levels and decreased insulin and insulin-like growth factor-1 signaling lead to loss of interstitial cells of Cajal, which results in abnormal gallbladder emptying and promotes gallstone formation." (PMID 31088424, 2019). "Prime biomarker candidates in pregnancies with diabetes include maternal glycaemic markers (glucose, 1,5-anhydroglucitol, glycosylated hemoglobin) and hormones proposed implicated in placental nutrient transfer (adiponectin and insulin-like growth factor-1)." (PMID 30108547, 2018). "Poor glycemic control as observed at diabetes onset in this study is associated with low IGF-1." (PMID 29744370, 2018). "Among the reasons that cause such subgroup differences, highly expressed IGF-1 by the diabetes for the CRC patients might be regarded as one reason that severely associate with the colorectal cancer risk by the anatomic subsite." (PMID 28977962, 2017). "Secondly, hyperinsulinemia exists in most T2DM patients during the early period of diabetes, and might be another potential cancer risk due to its role in biological cell proliferation via the IGF–1 signaling pathway." (PMID 27271648, 2016). "In addition, IGF-1 levels in childhood and adolescence are predictive of IGF-1 levels in adulthood, and lower levels of IGF-1 in adults have been associated with diabetes, cardiovascular diseases, and an increased risk of mortality." (PMID 26794451, 2016). "Whether diabetes increases cancer risk through hyperinsulinemia alone or due to its combined effect on insulin and IGF-1 is still unclear." (PMID 25996963, 2015). "We hypothesized that Acu-LFES would upregulate the IGF-1 signaling pathway, resulting in suppressed diabetes-induced muscle loss." (PMID 26230945, 2015). "Accumulating evidence indicates that insulin-like growth factor-1 (IGF1) acts as a homeostatic modulator for normal brain functionality and synaptic plasticity, and the loss of IGF1 activity caused by diabetes may contribute to cognitive impairment." (PMID 25268761, 2014). "IGF-1 may probably be involved in the metabolic abnormalities and complications associated with diabetes." (PMID 24364912, 2013). "GH and IGF-1 excess also causes several metabolic changes, including glucose intolerance and overt diabetes mellitus (DM)." (PMID 39859181, 2025). "The mechanisms by which diabetes predisposes individuals to cancer are not fully understood; however, researchers suggest that insulin-like growth factors (IGF-1 and IGF-2) and the stimulating effects of hyperglycemia on cancer cell proliferation may play significant roles." (PMID 39682196, 2024). "Excessive GH and insulin-like growth factor-1 (IGF-1) secretion causes progressive somatic disfigurement (mainly involving the face and extremities) and various systemic complications such as hypertension, diabetes, myocardial damage, sleep apnea syndrome, and malignant tumors." (PMID 39170435, 2024). "Metabolically, there has been an increased incidence of acromegaly-associated diabetes mellitus (DM), IGF-1 being the primary mediator, affecting the patient's overall morbidity/mortality and associated surge in cardiovascular events." (PMID 39119396, 2024). "It has also been confirmed that IGF-1 serum level plays a key role in short-term outcomes (three months), whereas in the longer term, e.g., two years, the associations are weakened and attenuated by other factors, such as diabetes, smoking, hypertension and hyperlipidemia." (PMID 37371326, 2023).